BRCA2 (BRCA2 DNA repair associated)
Diseases named in the same sentence as BRCA2 in open-access papers (continued):
Sharing a sentence is not in itself a finding about the gene and the disease.
ovarian carcinoma (continued). "Initial attempts at clinical translation of PARP inhibition relied on a strategy of synthetic lethality targeting genetically vulnerable tumors such as BRCA1- and BRCA2-deficient breast and ovarian cancers." (PMID 25124282, 2014). "CIMBA studies have so far demonstrated that more than 25 SNPs are associated with the risk of developing breast or ovarian cancer for BRCA1 or BRCA2 carriers." (PMID 24698998, 2014). "Mutations in BRCA1 or BRCA2 are found in the majority of hereditary breast and ovarian cancers and greatly increase lifetime risk for both cancers." (PMID 24624361, 2014). "We have recently reported that Aur A and BRCA2 are mutually suppressed in ovarian cancer cells to control the RAS-associated genomic instability and tumorigenesis through the regulation of the cytokinesis and polyploidization." (PMID 24775809, 2014). "BRCA1 and BRCA2 genes are critical in homologous recombination DNA repair and have been implicated in familial breast and ovarian cancer tumorigenesis." (PMID 25526776, 2014). "According to the updated data in TCGA, BRCA1 and BRCA2 were non-synonymously mutated in 42 and 33 ovarian cancer cases, respectively, accounting for 12.9% and 10.1% of 325 patients." (PMID 25437005, 2014). "Women with BRCA1 and BRCA2 mutation carriers are at substantially elevated risk of developing ovarian cancer." (PMID 25494812, 2014). "Previous studies analyzing families with known BRCA2 mutations found young-onset breast and/or ovarian cancer BRCA2 mutation carriers to have a 3.5- to 10-fold increased risk and estimated 5% lifetime risk of developing PDAC relative to non-BRCA2 carriers." (PMID 24624093, 2014). "We found four SNPs associated with ovarian cancer risk with a p-trend<0.01 in BRCA1 or BRCA2 mutation carriers." (PMID 24698998, 2014). "Individuals who inherit one mutant allele for BRCA2 experience an increased risk for breast and ovarian cancer in adulthood, while individuals who inherit biallelic BRCA2 mutations have a high incidence of malignancies during childhood." (PMID 24489863, 2014). "OC patients with a family history of breast or ovarian cancer present high probability of carrying a mutation in BRCA1 or BRCA2." (PMID 25136623, 2014). "Using our validated workflow, we have identified 18 deleterious mutations in 101 patients (17,8%) which is in accordance with the prevalence of BRCA1 and BRCA2 mutations reported in the Spanish hereditary breast and ovarian cancer population." (PMID 25136594, 2014). "The BRCA genes do not demonstrate equal penetrance and the lifetime risk of developing epithelial ovarian cancer for women with a BRCA1 or BRCA2 mutation is up to 66% and 27%, respectively." (PMID 27382614, 2014). "Majority of mutations found to date in the BRCA1/BRCA2 genes in breast and/or ovarian cancer families are point mutations or small insertions and deletions scattered over the coding sequence and splice junctions." (PMID 24906410, 2014). "Mutation of breast cancer 1 and 2, early onset (BRCA1 and BRCA2) are known to influence ovarian cancer development and can be used as diagnostic or prognostic factors." (PMID 24551595, 2014). "Germline mutations that inactivate BRCA1 and BRCA2 are responsible for breast and ovarian cancer susceptibility." (PMID 25136594, 2014). "It is now appreciated in the ovarian cancer literature that upon treatment with standard platinum-based chemotherapy, BRCA1- and BRCA2-associated malignancies have an improved prognosis compared to sporadic epithelial ovarian cancers." (PMID 25177489, 2014). "Deleterious mutations in the BRCA1 or BRCA2 genes increase a woman's lifetime risk of breast and ovarian cancer." (PMID 24586286, 2014). "Although three other SNPs were found to be associated with ovarian cancer risk in BRCA2 mutation carriers (p-trend<10−3), these results were based on a relatively small number of ovarian cancer cases." (PMID 24698998, 2014).
ovarian carcinoma (continued). "In a Polish study, BRCA1 or BRCA2 germline mutations were found in 13.9% of consecutive ovarian cancer patients, 11% of which was attributable to BRCA1." (PMID 23536787, 2013). "Mutations in the breast and ovarian cancer-susceptibility genes, BRCA1 and BRCA2, confer an increased lifetime risk of ovarian cancer." (PMID 23591842, 2013). "Our results show the same associations between tumor Nmut and treatment outcome in both BRCA1- and BRCA2-associated ovarian cancers." (PMID 24265793, 2013). "The prevalence of BRCA1 and BRCA2 mutations in ovarian cancer patients varies amongst populations; a quite thorough population study in North America demonstrates a 13–15% frequency of germline BRCA1/2 mutations in sporadic ovarian cases." (PMID 23536787, 2013). "For women who carry the deleterious mutation in either of the BRCA genes, BRCA1 or BRCA2, the risk of developing breast or ovarian cancer is significantly increased." (PMID 23517070, 2013). "Both rs17631303 and rs183211 were associated with ovarian cancer risk for BRCA2 carriers (P = 1.98×10−4 and 9.26×10−4), with similar magnitude and direction of association as for BRCA1 carriers." (PMID 23544013, 2013). "The importance of BRC repeats in BRCA2 function has been demonstrated in patients with point mutations in this domain, which develop breast and ovarian cancer with much higher frequency than patients with mutations in other regions of the gene." (PMID 23675572, 2013). "Our observations suggest that the total mutation burden coupled with BRCA1 or BRCA2 mutations in ovarian cancer is a genomic marker of prognosis and predictor of treatment response." (PMID 24265793, 2013). "Ten years after the discovery of BRCA2 as a breast and ovarian cancer susceptibility gene, it was found to be the same gene as FancD1, i.e., one of the genes causing the childhood disease Fanconi anemia (FA), upon bi-allelic mutation." (PMID 23344037, 2013). "Further studies are warranted to determine the prevalence of mutations in the rest of the BRCA1 gene, in the BRCA2 gene, and other novel predisposing genes for breast and ovarian cancer." (PMID 23536787, 2013). "The 17q21.31 locus was also associated with ovarian cancer risk in 8,211 BRCA2 carriers (P = 2×10−4)." (PMID 23544013, 2013). "Still, the majority of hereditary cases, particularly those with mutations in BRCA1 and BRCA2 and, interestingly, a fraction of sporadic ovarian cancer cases with a similar phenotype, have been postulated to share “BRCAness”." (PMID 23344037, 2013). "Only one wild allele of BRCA1 or BRCA2 is sufficient for DNA repair mechanism, so as in Knudson's model, and additional somatic loss of the wild-type allele is necessary to develop ovarian carcinoma in women with a germline BRCA mutation." (PMID 24063014, 2013). "Recent studies on BRCA1/BRCA2 have concluded that a germline mutation in BRCA1 or BRCA2 was associated with improved survival in ovarian cancer patients and BRCA2 carriers had the best prognosis (40–, 42)." (PMID 23964347, 2013). "BRCA1 and BRCA2 mutation carriers in these families are at the same risk level for breast and ovarian cancer as women from high-incidence families." (PMID 23536787, 2013). "BRCA1 and BRCA2 are considered tumor suppressor genes, and loss-of-function mutations confer a significantly increased risk of developing breast and ovarian cancer." (PMID 23964347, 2013). "Somatic BRCA1 and BRCA2 gene alterations have been reported in sporadic epithelial ovarian cancers including loss of expression, somatic mutations, and LOH (deletions)." (PMID 23289505, 2013). "Mutational analysis of BRCA1 and BRCA2 in hereditary breast and ovarian cancer families have also been reported in several Spanish regions, showing a heterogeneous prevalence of recurrent mutations according to the geographical area." (PMID 23683081, 2013). "Other lines of evidence show differences between BRCA1 and BRCA2 mutation-associated ovarian cancers." (PMID 24265793, 2013).
ovarian carcinoma (continued). "Germline mutations in the BRCA1 and BRCA2 genes contribute to approximately 18% of hereditary ovarian cancers conferring an estimated lifetime risk from 15% to 50%." (PMID 23536787, 2013). "On the other hand, BRCA1 or BRCA2 mutations besides the three most common ones have also been reported in Ashkenazi Jewish women with breast/ovarian cancer although at much lower frequencies." (PMID 23638402, 2013). "Loss of heterozygosity of the BRCA1 gene was found in 50%–70% of sporadic ovarian carcinomas and loss of heterozygosity of BRCA2 was found in 30%–50%." (PMID 23644885, 2013). "Clinical geneticists use the BWA to calculate BRCA1 and BRCA2 mutation carrier probabilities and breast/ovarian cancer risks, which are used to determine eligibility for genetic testing or to provide individually tailored clinical management." (PMID 22490389, 2012). "Eighteen patients (14 BRCA1; 4 BRCA2; age range 37–73 years, median 58) have developed ovarian cancer after receiving their positive mutation test results." (PMID 22187038, 2012). "Women who carry BRCA1 or BRCA2 genetic mutations appear to retain a high lifetime risk of developing ovarian cancer." (PMID 22962582, 2012). "Another two studies demonstrated that BRCA1 and BRCA2 mutations represent 10–15% of all ovarian cancers." (PMID 22187038, 2012). "In the mid 1990s, a classical linkage approach identified germline mutations in two genes, BRCA1 and BRCA2, which are associated with a high risk of developing both breast and ovarian cancer." (PMID 23028338, 2012). "Founder BRCA1 and BRCA2 mutations in Ashkenazi Jews in Israel: frequency and differential penetrance in ovarian cancer and in breast-ovarian cancer families." (PMID 23961350, 2012). "It is very clear that there is a benefit of using PARP inhibitors as a monotherapy in breast or ovarian cancer patients with mutations in BRCA1 or BRCA2." (PMID 24970153, 2012). "The BWA returns BRCA1 and BRCA2 mutation carrier probabilities and age specific breast/ovarian cancer risks in a 'Computed Results' Web page." (PMID 22490389, 2012). "Women with inherited mutations in BRCA1 on chromosome 17q21 or BRCA2 on chromosome 13q31 are at significantly higher risk of developing breast and ovarian cancer than women in the control population." (PMID 22330607, 2012). "Currently, we know that a woman who inherits a fault in one of two genes, BRCA1 or BRCA2, has a high risk of developing both breast and ovarian cancer." (PMID 23028338, 2012). "BRCA1 related ovarian cancer are diagnosed at an earlier age than sporadic ovarian cancer cases, while average age at diagnosis for BRCA2 mutation carriers is similar to sporadic cases." (PMID 23039163, 2012). "According to the literature, inherited mutations in the BRCA1 and BRCA2 tumour-suppressor genes, account for the majority of hereditary breast and ovarian cancer cases." (PMID 22923021, 2012). "Clinical geneticists use the BWA to calculate BRCA1 and BRCA2 mutation carrier probabilities and breast/ovarian cancer risks." (PMID 22490389, 2012). "Novel sequence variants in BRCA1 and BRCA2 have been found in Spanish families with multiple cases of breast and ovarian cancer." (PMID 22238615, 2012). "Genetic screening of the BRCA1 and BRCA2 genes is offered to families with high risk of breast and ovarian cancer." (PMID 22350158, 2012). "As 20% of high grade serous sporadic ovarian carcinomas have BRCA1 and BRCA2 mutations, the role of HR in ovarian cancer has been well established." (PMID 22253870, 2012). "Mutations in the BRCA1 and BRCA2 tumor suppressor genes account for 65–85% of all hereditary ovarian cancers." (PMID 22388872, 2012). "The first clinical study using the synthetic lethal concept was the use of PARP inhibitors in BRCA1 or BRCA2 mutated breast and ovarian cancer, which are intrinsically sensitive to PARP inhibition." (PMID 24970153, 2012).
ovarian carcinoma (continued). "Numerous studies demonstrate that mutations in BRCA1 or BRCA2 can predispose one to breast and ovarian cancer, among other cancers." (PMID 22962582, 2012). "BRCA2, a tumour-suppressor gene, encodes a protein involved in repair of chromosomal damage and is an indicator of increased risk of breast and ovarian cancer." (PMID 22919381, 2012). "Most families with detected BRCA1 or BRCA2 gene mutation are qualified for molecular testing on the basis of family history of breast or ovarian cancers." (PMID 22395474, 2012). "In mammalian cells, the pivotal RMP is BRCA2: loss of BRCA2 function predisposes to breast and ovarian cancer." (PMID 24970156, 2012). "A recent population-based study showed a combined BRCA1 and BRCA2 mutation frequency of 13.3% among 1,342 women with ovarian cancer." (PMID 22388872, 2012). "Mutations of the genes BRCA1 and BRCA2 are associated with a high lifetime risk of developing breast and/or ovarian cancer." (PMID 22187038, 2012). "For example, germline mutations in BRCA1, BRCA2, and Rad51D are well known to increase ovarian cancer risk." (PMID 23319948, 2012). "While it is well known that use of this model produces estimates of the probability a women carries a BRCA1 or BRCA2 mutation, it also estimates of risks of breast and ovarian cancers based on the genetic, personal and family history data provided by the user." (PMID 21352566, 2011). "For example, a woman who carries specific mutations in the BRCA1 or BRCA2 (BReast CAncer) genes has a much higher risk for breast and ovarian cancer over her lifetime than the general population." (PMID 22047175, 2011). "Mutations in BRCA1 and BRCA2 were found, respectively, in nine and three percent of breast and ovarian cancer patients." (PMID 21559243, 2011). "Different mutations in BRCA1 and BRCA2 genes have a different penetrance for breast and for ovarian cancer." (PMID 21232165, 2011). "In the most comprehensive of these studies, the authors identified 26 BRCA mutations (15 BRCA1 and 11 BRCA2) in 287 Greek breast/ovarian cancer families using dHPLC followed by direct sequencing." (PMID 22085629, 2011). "BRCA1-mutation carriers are diagnosed with ovarian cancer at a younger age (average age 52) compared to BRCA2-mutation carriers (age 62) and sporadic cases (age 63)." (PMID 22312502, 2011). "The BRCA1 and BRCA2 genes were found to be mutated in a large number of families with multiple cases of an early onset of breast and ovarian cancer." (PMID 21232165, 2011). "The major inherited susceptibilities to breast and ovarian cancers are germline mutations in either BRCA1 or BRCA2 which however, explain only small number of breast and ovarian cancer cases." (PMID 21639959, 2011). "Considering other risk modulating factors associated with breast and ovarian cancers, notably both diseases are found at high incidence among individuals carrying pathogenic BRCA1and BRCA2 germline mutations." (PMID 21436469, 2011). "Since no effective screening programme has yet been identified, prophylactic BSO should be advised to all high-risk women after they completed their family which will reduce the risk of ovarian cancer associated with BRCA1 or BRCA2 mutation by 70-96%." (PMID 22112691, 2011). "BRCA2-deficient ovarian cancer xenografts showed marked response to olaparib, carboplatin, and olaparib plus carboplatin, whereas BRCA2-proficient xenografts responded only to carboplatin and olaparib plus carboplatin." (PMID 21819606, 2011). "The identification of BRCA1 and BRCA2 gene mutations and their relationship to ovarian cancer has resulted in an awareness of family history in many women with ovarian cancer." (PMID 22112691, 2011).
ovarian carcinoma (continued). "In general, the mutation detection rates for BRCA1 and BRCA2 genes in the members of Slovenian families with breast and/or ovarian cancer are comparable with the mutation frequencies in these two genes reported for other countries." (PMID 21232165, 2011). "Individuals who carry an inherited mutation in the breast cancer 1 (BRCA1) and BRCA2 genes have a significant risk of developing breast and ovarian cancer over the course of their lifetime." (PMID 22312502, 2011). "Some of the patients had the ovaries removed because they were carriers of a mutation in BRCA1 or BRCA2, which sets them at high risk to develop ovarian cancer." (PMID 21785733, 2011). "For example, the probability of carrying a germline mutation in BRCA1 or BRCA2 is low unless a woman has a very strong family history of breast and/or ovarian cancer." (PMID 21352566, 2011). "Relationships between breast and ovarian carcinomas have been established, including association with a germline mutation in BRCA2 and the influence of reproductive steroid hormone receptors." (PMID 21714919, 2011). "BRCA2 is mutated in a significant proportion of individuals with familial breast and ovarian cancer." (PMID 21789034, 2011). "Mutations in BRCA1 and BRCA2 are highly penetrant and confer an increased risk of breast and ovarian cancer in carriers." (PMID 21232165, 2011). "CIMBA database contains demographic, clinical and epidemiological data from 15,700 BRCA1 and 8,600 BRCA2, mutation carriers including 12,700 breast cancer patients, 2,500 ovarian cancer patients and 9,100 unaffected patients from 42 centers over the world." (PMID 21639959, 2011). "Mean cumulative risks for breast and ovarian cancer in BRCA2 mutation carriers are 49% and less than 20% at 70 years of age, respectively." (PMID 21939546, 2011). "Incidence of BRCA1 or BRCA2 mutations among different sub-groups of Slovenian families with breast and ovarian cancer." (PMID 21232165, 2011). "Up to now, several comprehensive studies performed throughout Europe determined the mutation profiles of BRCA1 and BRCA2 in families with history of breast and ovarian cancer." (PMID 21232165, 2011). "By age 70, women with BRCA1 or BRCA2 mutations have been shown to have a 20–60% calculated risk of ovarian cancer." (PMID 21577260, 2011). "Women who have inherited mutations in the BRCA1 or BRCA2 genes have substantially elevated risks of breast and ovarian cancer." (PMID 20961453, 2010). "The cumulative risk of ovarian cancer to age 70 years for women with a BRCA1 or BRCA2 mutation is estimated at about 40% and 10%, respectively." (PMID 20122277, 2010). "Germline mutations in BRCA2 predispose to both breast and ovarian cancer making it a good candidate gene for prostate cancer etiology." (PMID 20585617, 2010). "LOH and copy number abnormalities are often associated with BRCA1, and BRCA2-associated breast or ovarian cancer." (PMID 20877358, 2010). "Germline mutations in BRCA2 predispose to breast and ovarian cancer with its predominant tumour suppressor function thought to be the repair of DNA double-strand breaks." (PMID 20585617, 2010). "Between 5 and 10% of all ovarian cancer cases are associated with inheriting a mutation in the BRCA1 or BRCA2 gene." (PMID 20069122, 2010). "Based on the current knowledge, it is reasonable to recommend prophylactic oophorectomy for BRCA1 or BRCA2 mutation carriers when childbearing is completed in order to reduce the risk of developing breast and ovarian cancer." (PMID 20961453, 2010). "A significant portion of ovarian cancer (OC) cases is caused by germ-line mutations in BRCA1 or BRCA2 genes." (PMID 19338682, 2009). "According to previously published results, this mutation accounts for 31% of the BRCA1 and BRCA2 mutations identified in Greek familial breast/ovarian cancer patients." (PMID 19491894, 2009).